TUBA1A (tubulin alpha 1a)
Diseases named in the same sentence as TUBA1A in open-access papers (continued):
Sharing a sentence is not in itself a finding about the gene and the disease.
Lissencephaly (continued). "The functions of certain lissencephaly genes, including LIS1, DCX, and TUBA1A, are closely associated with microtubules, which, as integral components of the cytoskeleton, play crucial roles in cellular processes such as mitosis and cytokinesis." (PMID 39857780, 2025). "The genetic factors known to cause lissencephaly are DCX (double cortin), gene TUBA1A (tubulin alpha 1a), ACTB (actin beta), ACTG1 (actin gamma 1), and ARX (aristaless-related homeobox)." (PMID 39040723, 2024). "Lissencephaly (32.8% vs. 6.8%) with pachygyria and/or agyria was a distinctive cortical finding in TUBA1A compared with TUBB2B tubulinopathy (P < 0.001)." (PMID 33082561, 2021). "This includes lissencephaly (TUBA1A), polymicrogyria (TUBA1A, TUBB2B, TUBB3), microcephaly (TUBB2B, TUBB3, TUBB5, TUBG1), and oculomotor disorders (TUBB2B, TUBB3)." (PMID 33137126, 2020). "To date, TUBA1A represents the main tubulinopathy gene and accounts for 4–5% of all lissencephaly cases." (PMID 30744660, 2019). "Involvement of cerebellum in lissencephaly has been associated with the mutations of DCX, TUBA1A, and LIS1 genes, and represents a distinctive heterogeneous group of cortical malformations." (PMID 31355197, 2019). "A later report on the same patients mentioned that the two individuals with microcephaly and severe pachygyria resembled individuals with lissencephaly carrying the p.(Arg402Cys) substitution in TUBA1A." (PMID 29706637, 2018). "The core phenotype of TUBA1A-related tubulinopathies consists of lissencephaly, most frequently classic or with cerebellar hypoplasia." (PMID 29109381, 2017). "Tuba1a mutant mice, another lissencephaly model, are also hyperactive and exhibit prominent hippocampal lamination defects." (PMID 18575605, 2008). "Within this heterogeneous family, mutations of TUBA1A lead to lissencephaly (i.e., smooth and without gyri cerebral cortex), cerebellar hypoplasia, corpus callosum agenesis, severe developmental delay and epileptic seizures." (PMID 31940887, 2020). "While a few mutations leading to lissencephaly have been examined in terms of molecular and cellular consequence, to our knowledge none of the polymicrogyria-causing TUBA1A mutants have been investigated." (PMID 29057214, 2017). "In principle, any perturbation to cortical migration could lead to lissencephaly phenotypes, but most identified cases are attributed to mutations to LIS1 (also known as PAFAH1B1), doublecortin/DCX, and more recently TUBA1A." (PMID 29057214, 2017). "Although we have no histological data for these patients, these neurons were considered similar to those of the patient brain because a differentiation defect manifested by immature neurons and persistent radial glia was reported previously in the TUBA1A lissencephaly patient brain." (PMID 27431206, 2016). "Foetal TUBA1A tubulinopathies most often consist in microlissencephaly or classical lissencephaly with corpus callosum agenesis, but polymicrogyria may also occur." (PMID 25059107, 2014). "Retrospective assessment of the clinical and radiological features of this patient―i.e., microcephaly, lissencephaly (pachygyria) with cerebellar hypoplasia, and corpus callosum hypoplasia―indicated that the TUBA1A mutation did not lead to any contradictions." (PMID 25053001, 2014). "In contrast to the p.R402H mutation, which has been reported to cause lissencephaly without impairing either TUBA1A protein homeostasis or assembly into microtubules, we showed the p.I384N substitution impairs TUBA1A stability, preventing its incorporation into the lattice." (PMID 37435044, 2023). "Further sequencing of TUBA1A in patients without the characteristic cortical lissencephaly phenotype may prove fruitful in uncovering additional TUBA1A mutations." (PMID 29057214, 2017).
Lissencephaly (continued). "Based on our data from the iPSC-derived NPCs, we concluded that the pathology of p.N329S TUBA1A lissencephaly might start from the steps of differentiation or polarization from neural progenitor cells, leading to a migration defect in young neurons and lamination defects in the cerebral cortex." (PMID 27431206, 2016). "Interestingly, the neurites and glial fibers derived from the iPSC-NPCs of the lissencephaly patient A (with the p.N329S TUBA1A mutation) did not extend radially and displayed a shorter morphology." (PMID 27431206, 2016). "Mutations of many genes are involved in neuronal migration disorders, such as LIS1 and DCX in classical lissencephaly spectrum, TUBA1A in microlissencephaly with agenesis of the corpus callosum, and RELN and VLDLR in lissencephaly with cerebellar hypoplasia." (PMID 26052266, 2015). "Mutations in the tubulin alpha-1A gene (TUBA1A) are the most common cause of the cases of tubulinophaty, and mutations in this gene cause lissencephaly as a result of the lack of cytoskeletal integrity." (PMID 32033020, 2020). "For example, interference with neuronal migration can lead to lissencephaly, but not all the aspects of TUBA1A that are important for neuronal migration are known." (PMID 29057214, 2017). "In a recent summary of targeted sequencing studies for 17 genes in 811 patients with lissencephaly, a diagnostic rate of 81% was observed, in which > 99% of pathogenic variants were in LIS1, DCX, TUBA1A, or DYNC1H1, none of which are inherited in an autosomal recessive fashion." (PMID 33290415, 2020).
tubulinopathies (27 papers, 2014 to 2025). "This ultra rare and pathogenic mutation in the TUBA1A gene represents a new TUBA1A-associated tubulinopathy caused by a previously unpublished TUBA1A mutation and a phenotype that should not be conflated with canonical WWS." (PMID 39202391, 2024). "Heterozygous de novo TUBA1A mutations cause an autosomal dominant “tubulinopathy”, with clinical features including brain malformations, microcephaly, neurodevelopmental delay, motor impairment, cognitive deficit, and epilepsy." (PMID 39202391, 2024). "TUBA1A mutations are the most common cause of tubulinopathies with neurological phenotypes, and to date, all identified pathogenic TUBA1A mutations appear to be autosomal dominant heterozygous loss of function mutations." (PMID 39202391, 2024). "Mutations in tuba1a, tubb2a, and tuba4a have all been linked to a group of clinical neurodevelopmental disorders known as tubulinopathies." (PMID 39453165, 2024). "In one individual (#20) with MRI findings pointing to a tubulinopathy, genetic testing revealed a heterozygous de novo likely pathogenic variant in the TUBA1A gene." (PMID 37131188, 2023). "By presenting another case (i04), we here identify TUBA1A tubulinopathy as a rare but recurrent cause for this rare migrational disorder." (PMID 35017693, 2022). "Except for three familial cases, TUBA1A-tubulinopathy is exclusively caused by de novo missense variants scattered throughout the gene." (PMID 35017693, 2022). "TUBA1A tubulinopathy is a relevant cause of congenital brain malformations as well as early-onset and intractable epilepsy with semiologic diversity." (PMID 35017693, 2022). "Tubulinopathies are predominantly caused by variants in TUBA1A, encoding the major CNS α-tubulin isotype, which accounts for a rapidly growing number of more than 170 cases." (PMID 35017693, 2022). "For example, the TUBA1A-R402C/H tubulinopathy mutations are in a region predicted to be important for dynein binding." (PMID 36406756, 2022). "TUBA1A tubulinopathy is a rare neurodevelopmental disorder associated with brain malformations as well as early-onset and intractable epilepsy." (PMID 35017693, 2022). "In this study we investigate the molecular mechanism of two previously identified tubulinopathy-associated mutations at the valine 409 residue of TUBA1A, V409I, and V409A." (PMID 35511030, 2022). "To understand if we can decipher patterns between TUBA1A mutations and disease phenotype and/or severity, we mapped the tubulinopathy mutants in several ways." (PMID 36406756, 2022). "TUBA1A mutations are highly represented in cases of human tubulinopathies, suggesting that TUBA1A plays an important role in neurodevelopment." (PMID 35127710, 2021). "TUBA1A constitutes the majority of α-tubulin in the developing brain and mutations to TUBA1A in humans cause severe brain malformations accompanied by varying neurological defects, collectively termed tubulinopathies." (PMID 35127710, 2021). "TUBA1A represents the primary subunit gene linked to a group of tubulin disorders called “tubulinopathies”." (PMID 34638726, 2021). "As such, previous studies of tubulinopathy mutations have relied heavily on mRNA analysis and indirect methods of evaluating TUBA1A protein function." (PMID 35127710, 2021). "Heterozygous mutations that disrupt human TUBA1A are associated with severe brain malformations, termed tubulinopathies, suggesting that TUBA1A is critical for brain development." (PMID 32184299, 2020). "No deletions, frameshift, or nonsense mutations have been identified in association with TUBA1A tubulinopathy patients." (PMID 32184299, 2020). "We extensively reviewed and systematically reanalyzed available public data to provide a standardized synopsis of described variants together with reported neuroradiological and clinical features of TUBA1A-associated tubulinopathy." (PMID 30744660, 2019).
tubulinopathies (continued). "We conclude that Tuba1a is required for survival and that loss of Tuba1a leads to major cortical malformations with similarities to what is seen in the human tubulinopathy patients." (PMID 31386652, 2019). "Our efforts to systematically reanalyze published data enabled insights into the current state of information about TUBA1A-associated tubulinopathy." (PMID 30744660, 2019). "A thoroughly conducted clinical examination and the standardized reporting of phenotype and genotype information in online databases, e.g. ClinVar and LOVD are fundamental for the systematic analysis of rare diseases such as TUBA1A-associated tubulinopathy." (PMID 30744660, 2019). "Even though TUBA1A-associated tubulinopathy is the most common tubulinopathy form, our results indicate that more clinical and mutational information is necessary to evaluate a potential genotype-phenotype correlation." (PMID 30744660, 2019). "Anomalies of the corpus callosum ranging from partial to complete agenesis or hypoplasia are with 96.2% (102/106) the predominantly reported feature of TUBA1A-associated tubulinopathy." (PMID 30744660, 2019). "The TUBA1A-associated tubulinopathy is clinically heterogeneous with brain malformations, microcephaly, developmental delay and epilepsy being the main clinical features." (PMID 30744660, 2019). "TUBA1A mutations (as with other tubulinopathies) are often associated with hypoplasia/agenesis of the corpus callosum, hypoplasia/dysplasia of the cerebellum, and dysmorphic basal ganglia." (PMID 30087272, 2018). "We have shown that the TUBA1A c.5G>A, p.(Arg2His) mutation causes cortical, callosal, and cerebellar abnormalities that are typical of tubulinopathy-associated brain malformations." (PMID 30087272, 2018). "With the identification of tubulinopathy-causing TUBA1A mutations, understanding how TUBA1A must function during neural development becomes an urgent inquiry." (PMID 29057214, 2017). "The tubulin gene most commonly mutated in tubulinopathy patients is TUBA1A, the human isoform of α1 tubulin that is highly expressed in post-mitotic neurons." (PMID 29057214, 2017). "Identifying which category TUBA1A mutations fit into will greatly increase our understanding of tubulinopathy disease progression." (PMID 29057214, 2017). "Brain malformation disorders caused by mutations to TUBA1A and other neuronally expressed tubulin isotypes are collectively termed “tubulinopathies”, and lead to severe cortical abnormalities, mental retardation, and commonly epilepsy and paralysis." (PMID 29057214, 2017). "The increasing number of TUBA1A mutations discovered and the growing list of phenotypic consequences call for a greater understanding of the mechanism(s) of tubulinopathy disease progression." (PMID 29057214, 2017). "To conclude, the present study demonstrates that tubulinopathies, and more specifically TUBA1A mutations, represent one of the major genetic aetiologies of sporadic microlissencephalies." (PMID 25059107, 2014). "In this study, we identified a very rare TUBA1A mutation, His283Arg, located in the tubulin C-terminal domain (aa 263–392), in an infant that exhibited canonical tubulinopathy phenotypes with additional clinical features including some not previously reported with mutation of the gene." (PMID 39202391, 2024). "Moreover, among tubulinopathies, pathogenic variants in TUBA1A have been most frequently associated with lissencephaly." (PMID 36769099, 2023). "While some work has indicated that TUBA1A tubulinopathy mutations result in haploinsufficiency, more recent works have highlighted how patient mutations dispersed across the α-tubulin protein can act dominantly from within microtubules to alter dynamics and interactions with MAPs." (PMID 36406756, 2022).
tubulinopathies (continued). "TUBA1A has long been associated with neurodevelopment due to its spatial and temporal expression as well as its causal role in tubulinopathies, but cellular visualization of a single α-tubulin isotype or mutant has remained elusive due to the limited availability of isotype-specific tools." (PMID 35127710, 2021). "In contrast, several TUBA1A mutations have been found recurrently in tubulinopathy patients." (PMID 30087272, 2018). "Similarly, it is reasonable to consider that tubulinopathy mutations, such as TUBA1A-V409I/A and TUBB3-D417H/-R262H may have allosteric effects across the heterodimer that impact tubulin conformations and interactions with MAPs." (PMID 36406756, 2022). "Therefore, it is interesting to probe further into TUBA1A specific tubulinopathy mutations and determine if there are particular patterns or themes that we can draw from these studies about how particular regions influence TUBA1A biology and ultimately neurodevelopment." (PMID 36406756, 2022). "Mutations in seven genes encoding α- (TUBA1A), β- (TUBB2A, TUBB2B, TUBB3, TUBB4A, TUBB5), and γ- (TUBG1) microtubulin are linked to extensive overlapping brain malformations or tubulinopathies." (PMID 40948494, 2025). "The clinical diagnoses of PTBHS and tubulinopathy were confirmed by detection of causative variants in LAMA1 and TUBA1A, respectively." (PMID 37131188, 2023). "The broad range of phenotypic severity observed here underscores the clinical variability of TUBA1A tubulinopathy." (PMID 35017693, 2022). "We here extend the clinical, neuroradiological, and genetic spectrum of TUBA1A tubulinopathy and provide insights into residue-specific pathomechanisms and genotype-phenotype correlations." (PMID 35017693, 2022). "TUBA1A tubulinopathy is a rare neurodevelopmental disorder with a high burden of disease but clinical studies with sufficient cohort sizes are scarce." (PMID 35017693, 2022). "In this study, we complement clinical and genetic characteristics of TUBA1A tubulinopathy in a series of ten individuals with nine different missense variants." (PMID 35017693, 2022). "Other “tubulinopathies” genes include TUBA1A, TUBB2A, TUBB2B, TUBA8, TUBB3, TUBB, and TUBG1, which were found to be DEGAs in various brain regions." (PMID 34638726, 2021). "Recent analysis performed on TUBA1A loss-of-function mice and cultured fibroblasts from TUBB-associated tubulinopathy patients have revealed an impaired MT dynamics and aberrant cytoskeleton configurations in the axonal GCs." (PMID 34924953, 2021). "Other mutations in human α-and β-tubulin-encoding genes – such as TUBA1A, TUBB2B, TUBA8, TUBB4A, TUBB2A, TUBB – are linked to severe brain malformations and motor-cognitive disabilities, collectively refereed as tubulinopathies." (PMID 34924953, 2021). "From 144 reported cases, 120 individuals (83.3%) with TUBA1A tubulinopathy were born at term (gestational week [GW] 40)." (PMID 33082561, 2021). "Defined data on estimated survival, diagnostic delay, and disease characteristics of TUBA1A and TUBB2B tubulinopathy will help to raise disease awareness and encourage future clinical trials to optimize genetic testing, family counseling, and supportive care." (PMID 33082561, 2021). "Estimated survival analysis using the Kaplan–Meier method showed that 93.4% of individuals with TUBA1A tubulinopathy were still alive at the age of 3.2 years." (PMID 33082561, 2021). "The range of phenotypes exhibited by tubulinopathy patients have made it challenging for scientists to pinpoint specific aspects of neuronal function that are reliant on TUBA1A tubulin." (PMID 35127710, 2021). "Distinctive features included primary, progressive microcephaly and facial dysmorphisms in individuals with TUBA1A tubulinopathy." (PMID 33082561, 2021).